IGF1 (insulin like growth factor 1)
Diseases named in the same sentence as IGF1 in open-access papers (continued):
Sharing a sentence is not in itself a finding about the gene and the disease.
breast cancer (continued). "Patients with breast cancer tend to exhibit high serum levels of IGF-1, and activation of the IGF gene signature has been observed in triple-negative or basal-like breast cancer cell lines." (PMID 31505803, 2019). "Upregulated Dvl3 was also recently investigated as a biomarker for the recurrence of prostate cancer, while its downregulation sensitizes prostate and breast cancer cells to insulin-like growth factor 1 (IGF1)." (PMID 31126091, 2019). "In MCF-7 breast cancer cells, insulin-like growth factor-1 (IGF-1) activates the GPER promoter and increases the GPER transcription through the IGF-IR/PKCδ/ERK pathway." (PMID 31708873, 2019). "CYR61 is overexpressed in glioblastoma and breast cancer cells and regulates proliferation through Integrin/Insulin-like growth factor 1 (IGF1)-AKT signaling pathways." (PMID 31541175, 2019). "Mice with elevated growth hormone (GH)/Igf1 serum concentration had a higher incidence and reduced latency of mammary tumours but only in the context of a high fat diet." (PMID 31179642, 2019). "The 10% FS-induced inhibition of breast cancer growth and metastasis was related to the downregulation of insulin-like growth factor 1 and epidermal growth factor." (PMID 31689992, 2019). "Support for this statement comes from the preliminary evidence of benefit from xentuzumab in breast cancer patients with predominant bone metastases, and prostate cancer patients whose tumors express high IGF1 mRNA." (PMID 31416218, 2019). "Doxorubicin (1 μM) was found to significantly stimulate the expression of PLG (plasminogen, downregulated by Twist1 inhibitors; ANGPT2 (involved in breast cancer metastasis in brain); IGF-1 (a stimulator of TWIST1) and GLI1 (activated upon TWIST1 activation)." (PMID 31331001, 2019). "In a randomised controlled trial examining the effects of exercise in overweight or obese breast cancer survivors, circulating biomarkers (insulin, IGF‐1, adiponectin and leptin) were significantly improved post‐intervention, compared to usual care." (PMID 31016867, 2019). "A large body of clinical, experimental and epidemiological data supports the concept that activation of the insulin and IGF1 signaling pathways is a critical requisite for breast cancer progression." (PMID 31771180, 2019). "IGF1 is a key growth factor of mammary terminal end bud and ductal formation during development; however, it also plays an important role in breast cancer development, progression and metastasis." (PMID 30185144, 2018). "In both MCF7 breast cancer cells and J82 bladder cancer cells, the IGF-1 secretion was greatly stimulated by rhGH." (PMID 29983893, 2018). "IGF1 increased motility of metastatic MDA-MB-231BO breast cancer cells through activation of the IGF1R and a dominant negative mutant of IGF1R decreased adhesion, invasion and metastasis of MDA-MB-435 cells." (PMID 30348128, 2018). "Under an obese state in breast cancer, leptin interacts with molecular effectors such has estrogen, insulin, IGF-1 and inflammatory cytokines, which impacts various stages of breast cancer from initiation to metastatic progression." (PMID 30567335, 2018). "Numerous studies suggested that the IGF1 system is a promising candidate in breast cancer therapies." (PMID 30185144, 2018). "More recently, it was reported that tranilast, an anti-allergic agent, attenuates Ca2+ influx and cytosolic Ca2+ oscillations evoked by insulin-like growth factor-1 (IGF-1) in the ER+ (estrogen receptor positive) breast cancer MCF7 cell line." (PMID 30558192, 2018). "Breast cancer-specific routes and specific key mediators are emerging within the canonical IGF-1 signaling transduction pathways that lead to EMT activation." (PMID 30111747, 2018). "These clinical investigations have revealed that high levels of serum IGF-1 and/or decreased concentrations of IGF-1 binding proteins are linked to an augmented risk for several malignancies, including breast cancer, prostate, lung, and colorectal cancer." (PMID 29983893, 2018).
breast cancer (continued). "IGFBP1 and IGFBP3 genes are located adjacent to each other and are important regulators of bioavailability of IGF-1, which stimulates proliferation of breast cancer cell lines and primary culture." (PMID 30400783, 2018). "Recent studies have suggested that the level of circulating IGF-1 is higher in patients with pheochromocytoma, glioma, breast cancer or prostate cancer." (PMID 30213025, 2018). "We demonstrate that ASCs with abnormal chromosomal number enhance the proliferation of breast cancer cells via insulin-like growth factor 1 (IGF1) production." (PMID 30185144, 2018). "In another study, vitamin D analogs EB1089 and CB1093 promoted apoptosis in breast cancer cells by suppressing insulin-like growth factor 1 (IGF1) signaling." (PMID 29849001, 2018). "In biological assays, we showed that IGF1 requires both HIF-1α and GPER to induce VEGF-mediated endothelial tube formation, as evidenced by HUVECs cultured with conditioned medium obtained from CAFs and breast cancer cells treated with IGF1." (PMID 29212519, 2017). "In this respect, MEMO1 was reported to act at the intersection between growth factor (heregulin and IGF1) and estrogen signaling in breast cancer cells." (PMID 28425924, 2017). "IGF-1 is an important mediator of mammary terminal ductal formation during development, and increased activity of the gland’s IGF-1/IGF1R system has been shown to play a major promoting role in the development of breast cancer." (PMID 28822014, 2017). "Although IGF-1 has been well demonstrated to enhance breast cancer cell proliferation, only a small subset of miRNAs are shown to be significantly regulated by IGF-1 treatment in breast cancer." (PMID 29162853, 2017). "Additional studies suggest that tumors in obese breast cancer patients, particularly ER/PR-negative tumors, are dependent of growth factors such as insulin, insulin growth factor 1 (IGF1), and leptin." (PMID 28607775, 2017). "Insulin was found to favour growth of breast cancer cells, and insulin increases proliferation of the MCF-7 breast cancer cell line, and IGF1 is a potent mitogen for osteosarcoma cells." (PMID 28316059, 2017). "There is a crosstalk between IGF‐1/mTOR pathway and ER signalling in endocrine‐resistant breast cancer." (PMID 28272775, 2017). "Downregulation of AIB1 (“Amplified in breast cancer 1”) by miR-17-5p decreased proliferation and abrogated insulin-like growth factor 1-mediated, anchorage-independent growth of breast cancer cells." (PMID 29050357, 2017). "In the present study we used as model systems patient-tumor derived CAFs and SKBR3 breast cancer cells, which allowed us to characterize the IGF1/IGF1R action in ER-negative breast cancer cell setting." (PMID 29212519, 2017). "Collectively, these data provide evidence on the molecular mechanisms activated by IGF1 through GPER toward the regulation of VEGF expression in breast cancer cells." (PMID 29212519, 2017). "Using the T47D breast cancer cell line, IGF-1 induced substantial CELx signals through IGF-1R with an average Delta CI of 0.4." (PMID 28302091, 2017). "Its overexpression promotes anoikis resistance and enhances tumorigenesis in HER2− breast cancer cell lines via IGF-1 signaling." (PMID 28409241, 2017). "Altogether, these findings suggest that HIF-1α and its transcriptional targets GPER and VEGF are triggered by IGF1 both in breast tumor microenvironmentally derived CAFs and in luminal breast cancer cells." (PMID 29212519, 2017). "Insulin-like growth factor-1 (IGF-1) signaling is associated with various types of cancers, including pancreatic, lung and breast cancers." (PMID 28046018, 2017). "In 1998, a link between elevated insulin-like growth factor 1 (IGF1) blood levels and breast cancer risk in premenopausal women has been published." (PMID 29100507, 2017).
breast cancer (continued). "We establish in primary patient-derived breast CAFs, and in luminal breast cancer cells that IGF1 triggers the expression of VEGF and its transcriptional regulators HIF-1α and GPER, through the ERK1/2 and AKT transduction pathways." (PMID 29212519, 2017). "Insulin-like growth factor-1 (IGF-I) is an important mediator of cellular proliferation and is strongly linked to the progression of a number of human cancers, including breast cancer." (PMID 28079144, 2017). "Curcumin suppresses IGF-1R gene expression at transcriptional level, down-regulates IGF-1 axis and blunts IGF-1-stimulated breast cancer cell growth and reverses the IGF-1-induced apoptosis resistance." (PMID 28724427, 2017). "In relation to breast cancer risk, obese carriers of G6PC2, IGF1, and GCKR had an association with increased risk." (PMID 28446149, 2017). "IGF-1 plasma or serum levels have been reported to be increased in patients with a variety of cancers, including colorectal adenoma, malignant melanoma, breast cancer, non-small cell lung cancer." (PMID 28143425, 2017). "Circulating levels of IGF1 and IGFBP3 have also been linked to all cause mortality and development of breast cancer in some reports, but studies are conflicting." (PMID 28966806, 2017). "Mechanisms influencing breast cancer (BC) development and recurrence include hyperglycemia, hyperinsulinemia, high insulin-like growth factor-1, high circulating estrogen, inflammation and impaired cellular differentiation/apoptosis." (PMID 28114909, 2017). "Enrichment analysis of gene sets from 24 mouse models for breast cancer pinpoint to a potential new function for insulin-like growth factor 1 (Igf1r) in the basal epithelium during lactogenesis." (PMID 27808166, 2016). "Forced expression of Klotho was previously shown to inhibit MCF7 breast cancer cell growth by inhibiting insulin/IGF-1/AKT signaling." (PMID 26556877, 2016). "Although the Grb2/Ras/MAP-kinase pathway is not involved in the anoikic resistance of oestrogen-responsive breast cancer cells, its inhibition induces significant cell death which is abrogated almost completely by IGF-1." (PMID 26801096, 2016). "In animal experiments, selective knockout of IGF-1 gene causes reduction of IGF-1 level in circulation, and occurrence rate of breast cancer significantly decreased." (PMID 27835910, 2016). "Increased level of insulin and IGF-1 in central obesity were mitogenic agents and promoted breast cancer cell proliferation directly." (PMID 27247890, 2016). "We also found that protein restriction, independently of caloric intake, strongly inhibits tumor growth in human xenograft prostate and breast cancer animal models, by lowering serum IGF‐1 and reducing mTOR phosphorylation." (PMID 26443692, 2016). "We examined the associations of 22 polymorphisms across five IGF1 pathway genes (IGF1, IGFBP3, IGF1R, IRS1, and PI3KCB) with risk of breast cancer among women of European and East Asian descent." (PMID 27376028, 2016). "Models for anoikis of oestrogen-responsive breast cancer cells were established and the protective effects of IGF-1 tested." (PMID 26801096, 2016). "In this study, we provided the novel evidence that host EphA4 deficiency inhibited murine breast cancer growth and metastasis by reducing the EphA4‐GH receptor (GHR)‐IGF1 and/or EphA4‐IGF1 activities, which lead to decreasing IGF1 production." (PMID 26923183, 2016). "To further confirm that compound 2 was capable of altering an IGF-1R signaling network we made use of an 800 gene large signature identified in breast cancer (BC) cells upon IGF-1 treatment." (PMID 27384680, 2016). "We demonstrate the importance of the intrinsic pathway in anoikis and that IGF-1 can reinstate anoikis resistance of unattached oestrogen-responsive breast cancer cells cultured in serum-free medium." (PMID 26801096, 2016).
breast cancer (continued). "Chronic stimulation by GH/insulin-like growth factor-1 (IGF-1) has been described as a potential pathophysiologic explanation, with clinical evidence available outside of the acromegaly setting, for breast cancer, colorectal cancer and prostate cancer." (PMID 25996963, 2015). "Here, we treated MCF7 cells with a significant breast cancer-related growth factor, IGF-1, in a time course, from 6 to 30 h." (PMID 25956506, 2015). "We report the case of a 72-year-old man who was diagnosed with acromegaly (IGF-1 770 ng/ml) and breast cancer." (PMID 25962899, 2015). "IGF-1, after binding to its receptor, is also known to increase the proliferation rate of estrogen-dependent breast cancer cell lines." (PMID 25962899, 2015). "Specifically IGF1, whose expression is elevated in human breast cancer, is known to increase breast cancer cell growth and invasion." (PMID 26100469, 2015). "In vitro work in MCF7 breast cancer cells demonstrated that BRCA1 knockdown induces the expression of IGF-1 mRNA in an estrogen receptor α-dependent manner, which was shown to correspond with increased IGF-1R activation and signaling." (PMID 26217584, 2015). "The insulin-like growth factor (IGF-1)/insulin signaling axis has widely been reported in modulating breast cancer anti-estrogen drug resistance." (PMID 25956506, 2015). "In breast cancer cells expressing PR-B, it was shown that mifepristone blocked the migration induced by IGF1." (PMID 25252652, 2015). "IL-6 levels were associated with chronological age in both groups and with clinical frailty in older breast cancer patients, whereas telomere length, IGF-1 and MCP-1 only correlated with age." (PMID 25989735, 2015). "In vitro experiments treating breast cancer cell lines overexpressing HRs with IGF-1 induced greater auto-phosphorylation compared to IGF-1R homodimers." (PMID 26217584, 2015). "IGF-1 appears to be a direct target of miR-190b and another study have demonstrated that IGF-1 and ER expressions are raised in breast cancer cases which were likely to develop tamoxifen resistance." (PMID 26141719, 2015). "Similar to breast cancer cells, in vitro studies have shown that endometrial cancer cell lines increased proliferation by activation of insulin, IGF-1, and ovarian steroid hormone signaling pathways, such as estrogen and androgen signaling pathways." (PMID 25866823, 2015). "To further understand the underlying mechanism of the decreased tumor latency by IGF1 and X10, we determined the expression of proteins in the main signaling pathways associated with IR and IGF1R signaling as well proteins used in breast cancer classification." (PMID 25848982, 2015). "The use of a gene expression patterns has been previously reported in breast cancer, in which IGF-1 treated MCF-7 cells were profiled for RNA transcription 3 and 24 h following treatment." (PMID 26217584, 2015). "We then treated 293 cells with IL-1β for different times, and treated breast cancer MCF7 cells with IGF-1 for 1h." (PMID 26318844, 2015). "Recently, it has been demonstrated that IGF-1 cooperates with CXCR4 signaling to promote bone marrow metastasis of breast cancer, potentially one factor in the aggressive behavior of LumB tumors." (PMID 25632947, 2015). "According to Bruchim and Werner, IGF-1 also stimulates potassium chloride cotransporters, which are required for the invasion and proliferation of cervical, ovarian and breast cancer cells." (PMID 25384883, 2015). "RANTES enhances the motility, invasion and metastasis of breast cancer cells, and IGF-1 enhances extracellular matrix production." (PMID 26076490, 2015). "Higher bioactive levels of IGF1, most accurately represented by the molecular ratio of circulating IGF1 to IGFBP3, have been shown to be associated with breast cancer mortality." (PMID 25619494, 2015). "Mifepristone blocked the secretion of IGF1 induced by progesterone and E2 in ex vivo explants of ER-positive/PR-positive breast cancers." (PMID 25252652, 2015).
breast cancer (continued). "Insulin-like growth factor-1 (IGF-1) is another potent factor that stimulates breast cancer progression and mediates anti-estrogen drug resistance." (PMID 25956506, 2015). "All three EDCs–PCB 153, phthalates, and BPA influenced five common genes—CYP19A1, EGFR, ESR2, FOS, and IGF1—in breast cancer as well as in endometriosis." (PMID 26512648, 2015). "The ratio between IGF-1 and serum IGFBP-3 was associated with increased mortality, suggesting a potential prognostic biomarker value of this ratio in breast cancer." (PMID 26217584, 2015). "Our findings suggest AGR2 induction as a novel IGF-1-induced breast cancer formation mechanism, relevant to both the activation of the ER and the non-ER pathways." (PMID 25956506, 2015). "A previous study indicated that IGF-1 can activate EREs through ERs mediated transcriptional activation in breast cancer." (PMID 26587829, 2015). "Several studies have provided new insights into the biological effects of insulin-like growth factor 1 (IGF-1) ligand in epithelial to mesenchymal transition (EMT) in breast cancers." (PMID 25749031, 2015). "To further confirm how AGR2 induction contributes to IGF-1-induced breast cancer development, we investigated AGR2-knockdown effect on the IGF-1-induced cell proliferation, cell migration and cell cycle distribution." (PMID 25956506, 2015). "Although many of the relevant molecular pathways and intracellular cascades remain to be elucidated, a growing body of evidence points to the important role of the IGF-1 system in breast cancer development, progression and metastasis." (PMID 25743390, 2015). "Both IGF-1 and insulin are mitogenic and anti-apoptotic for human breast epithelium and also human breast cancer cells; human breast cancer cells often overexpress IGF-1 receptor and insulin receptor." (PMID 26030767, 2015). "In canine mammary carcinoma, tissue GH (Growth Hormone) and IGF-1 have been positively correlated with tumor malignancy, as well as with tissue levels of progesterone and 17β-estradiol." (PMID 26449867, 2015). "Given the known associations between Cyr61 and invasion, IGF-1 and breast cancer, and the potential interactions through the IGFBP domain on Cyr61, we investigated the role of IGF-1 on Cyr61 induced cell growth and invasion." (PMID 25062088, 2014). "Next, we examined IGF-1/AKT signaling pathway in APP-kd cells since AKT/FOXO signaling axis have been identified as critical signaling intermediates for breast cancer survival, growth, and migration as well as therapeutic drug resistance." (PMID 25491510, 2014). "In order to investigate the effects of IGF-1 and its mediated pathways on Cyr61 expression, proliferation, and invasion in breast cancer, a cell model system was utilized which includes MCF-7 WT and a MCF-7 Cyr61 transfectant clone." (PMID 25062088, 2014). "The Giα proteins associated with RTKs, Gab1, FRS2 and Shp2 in breast cancer cells and their ablation impaired Gab1’s interactions with Shp2 in response to EGF and IGF-1, or with FRS2 and Grb2 in response to bFGF." (PMID 24521094, 2014). "Further, Giα proteins can differentially regulate the activation of Akt, mTORC1 and ERK1/2 by EGF, bFGF and IGF-1 in breast cancer cells." (PMID 24521094, 2014). "Integration of phosphoproteomics and computational modelling of insulin-like growth factor-1 (IGF-1) signalling in breast cancer was used to predict optimal drug combinations that target IGF-1 and inhibit VEGF expression." (PMID 24237862, 2014). "Next, we examined the effects of IGF-1 treatment on breast cancer cell proliferation, invasion, and Cyr61 expression in relation to the PI3K/Akt pathway." (PMID 25062088, 2014). "There is substantial experimental evidence that the growth hormone/insulin IGF-1 axis not only affects the proliferative behaviour of breast cancer, but also stimulates proliferation of normal breast epithelial cells." (PMID 25285159, 2014).